THAP7 (THAP domain containing 7)
Description:
Chromatin-associated, histone tail-binding protein that represses transcription via recruitment of HDAC3 and nuclear hormone receptor corepressors.
Synonyms: MGC10963
Tractability: PROTAC: ubiquitination databases record sites on it.
Gene: Protein-coding gene on chromosome 22 (20,999,104 to 21,002,196, reverse strand). Ensembl gene ENSG00000184436.
Subcellular location: Nucleus; Chromosome
Subcellular location (Human Protein Atlas): Nucleoplasm; Nuclear membrane; Vesicles
Gene Ontology:
Molecular function: C2H2 zinc finger domain binding; general transcription initiation factor binding; histone deacetylase binding; histone H4 reader activity; histone reader activity; identical protein binding; protein binding; transcription corepressor binding
Biological process: chromatin organization; negative regulation of DNA-templated transcription; negative regulation of transcription by RNA polymerase II; regulation of DNA-templated transcription
Cellular component: chromatin; nuclear speck; nucleoplasm; nucleus; chromosome
Genetic constraint (gnomAD): Loss-of-function variants: 22 observed, 27.39 expected, observed/expected ratio (o/e) 0.8, 90% interval 0.57 to 1.15. The synonymous counts are far from expectation, so gnomAD's model fits this gene poorly and the ratio says little. Missense variants: 448 observed, 388.65 expected, observed/expected ratio (o/e) 1.15, 90% interval 1.07 to 1.25. Synonymous variants: 208 observed, 165.56 expected, observed/expected ratio (o/e) 1.26, 90% interval 1.12 to 1.41.
Homologues: Orthologues: chimpanzee THAP7 (99% identical), macaque THAP7 (99% identical), guinea pig THAP7 (98% identical), pig THAP7 (97% identical), mouse Thap7 (93% identical), rat Thap7 (84% identical), tropical clawed frog thap7 (56% identical), zebrafish thap7 (40% identical), Drosophila melanogaster CG13894 (10% identical). Paralogues in human: THAP2 (17% identical), THAP3 (17% identical), THAP8 (16% identical), THAP1 (16% identical), ARL14EP (9% identical), THAP6 (9% identical), ARL14EPL (5% identical).
Diseases named in the same sentence as THAP7 in open-access papers:
THAP7 is named in the same sentence as 5 diseases in open-access papers, as found by Europe PMC text mining. Sharing a sentence is not in itself a finding about the gene and the disease. The quoted sentences say what the papers report.
bipolar disorder (1 paper, 2023). A disorder of the brain that causes unusual shifts in mood, energy, activity levels and the ability to carry out day-to-day tasks. "However, we can identify five top genes at 22q11.2 associated with BMI (YDJC, CCDC116, PPIL2, THAP7, UBE2L3), primarily located outside the canonical CNV region (LCR D-E), three with bipolar disorder (TMEM191B, TUBA8, PPIL2), six with ASD (CLTCL1, AC004471." (PMID 37267418, 2023).
hepatoma (1 paper, 2022). "Notably, THAP7 overexpression induces permissiveness of human hepatoma Huh7 cells to hepatitis C viral invasion." (PMID 35328087, 2022).
infection (1 paper, 2019). The state of being infected such as from the introduction of a foreign agent such as serum, vaccine, antigenic substance or organism. "For THAP7, we found its knockdown to have a highly significant impact on HCV replication, both in the infection assay as well as in stable replicon cells." (PMID 31905685, 2019). "Overexpression of THAP7 resulted in a highly significant 5.5-fold increase (at 72 h) in replication of the subgenomic HCV replicon, and successfully rescued HCV replication by one log upon infection with JcR2a." (PMID 31905685, 2019).
THAP7 also shares sentences with these, for which no sentence is quoted: chronic kidney disease (1 paper); glioma (1).